INA (internexin neuronal intermediate filament protein alpha)
Diseases named in the same sentence as INA in open-access papers:
INA is named in the same sentence as 60 diseases in open-access papers, as found by Europe PMC text mining. Sharing a sentence is not in itself a finding about the gene and the disease. The quoted sentences say what the papers report.
Arrhythmia (11 papers, 2013 to 2025). Any cardiac rhythm other than the normal sinus rhythm. "Loss-of-function of INa and ICa–L, caused by mutations in SCN5A and calcium channel genes, respectively, has been associated with inherited cardiac arrhythmias, such as BrS and short QT syndrome." (PMID 41552678, 2025). "In HF, pathological CaMKII signaling promotes cardiac arrhythmia by influencing ion channel activities including INa, ICaL and various potassium currents." (PMID 34062838, 2021). "Several studies demonstrated that augmentation of the current can lead to cardiac arrhythmias; therefore, INa,late is considered as a promising antiarrhythmic target." (PMID 33258400, 2021). "Twelve studies indicated significant beneficial effects of NC in cardiac arrhythmia primarily through the modulation of ion channels (Ik, Ik1, INa, ICa-L, Ito)." (PMID 28797251, 2017). "GA not only blocks the HERG channel, IK (IKr, IKs), but also inhibits INa, so the results reveal that it has significant potential for development as a novel antiarrhythmic agent, particularly targeting the genesis of arrhythmias." (PMID 24069049, 2013). "Therefore, more work is necessary to gain a better understanding of the role of INa,late and Ca2+ handling in cardiac arrhythmias and to develop novel antiarrhythmic therapies with a focus on translational aspects." (PMID 33258400, 2021). "IK1 and INa play a key role in regulating cardiac excitability under physiological conditions and in the control of the frequency of the rotors that are responsible for fibrillating arrhythmias." (PMID 29184507, 2017). "In addition, Nardostachyos Radix Et Rhizoma (Gan Song) exhibited the cardioprotective effects via inhibiting myocardial apoptosis, inflammation, oxidative stress and showed a great promise as a novel option for arrhythmia by regulating several ion channels (Ik, Ik1, INa, ICaL, and Ito)." (PMID 30233380, 2018).
glioma (4 papers, 2008 to 2023). A benign or malignant brain and spinal cord tumor that arises from glial cells (astrocytes, oligodendrocytes, ependymal cells). "It is known that gliomas are characterized by the differential expression of voltage-gated sodium channel subtypes, which determine the expressed INa phenotype." (PMID 36831869, 2023). "INA is overexpressed mostly in oligodendroglia phenotype gliomas and correlated with better PFS and OS." (PMID 34395274, 2021). "INA is overexpressed mostly in oligodendroglial phenotype gliomas and is related to 1p/19q codeletion with >70% specificity." (PMID 32783304, 2020). "Forty‐six glioma samples and one non‐neoplastic brain sample were analyzed by MS‐HRM in terms of SFRP1, SFRP2, RUNX3, CBLN4, INA, MGMT, and RASSF1A promoter methylation." (PMID 32783304, 2020).
Brugada syndrome (3 papers, 2017 to 2024). A genetically heterogeneous condition characterized by complete or incomplete right bundle branch block accompanied by ST elevation in leads V1-V3. "Other genes, such as SCN1B, SCN2B, SCN3B, and GPD1L, contribute to reduced INa and Brugada syndrome, with various clinical phenotypes associated with these mutations." (PMID 39583597, 2024).
brain tumor (2 papers, 2020 to 2025). "The results of the MS‐HRM analysis of all analyzed genes (SFRP1, SFRP2, RUNX3, CBLN4, INA, MGMT, and RASSF1A) showed that their promoter sequence methylation level is significantly higher (P < 0.0001) in DNA samples from brain tumor patients than in the non‐neoplastic brain sample." (PMID 32783304, 2020).
epilepsy (2 papers, 2021). A brain disorder characterized by episodes of abnormally increased neuronal discharge resulting in transient episodes of sensory or motor neurological dysfunction, or psychic dysfunction. "This indicates that PDPN and ABCC3 are risk genes, and INA is a protective gene for LGG patients with epilepsy." (PMID 34336837, 2021). "Further, three prognostic DEGs (ABCC3, INA, and PDPN) were identified between high and low immune score groups in LGG patients with epilepsy." (PMID 34336837, 2021). "An immune-related gene signature was established based on ABCC3, PDPN, and INA, which can be used to predict the prognosis, immune infiltration status, immunotherapy and chemotherapy response of LGG patients with epilepsy." (PMID 34336837, 2021).
heart failure (2 papers, 2018). Inability of the heart to pump blood at an adequate rate to meet tissue metabolic requirements. "We are currently investigating if decreased IK1 and INa in heart failure is related to loss of caveolae or Cav3 regulation." (PMID 30473666, 2018). "Due to the complexity we have observed of cell type (modeling experiments) and the differences in effects by CAV3 mutations on IK1 and INa, we anticipate that there may also be a complex effect in heart failure on Kir2.x and Nav1.5 remodeling." (PMID 30473666, 2018). "Remodelling of INa channel has also been identified in heart failure and cardiac ischaemia." (PMID 30500818, 2018).
ischemia (2 papers, 2018 to 2025). A hypoperfusion of the BLOOD through an organ or tissue caused by a PATHOLOGIC CONSTRICTION or obstruction of its BLOOD VESSELS, or an absence of BLOOD CIRCULATION. "Thus, the D14601E TTN missense mutation was expected to predispose to ischemia-related VF by affecting the function of INa and ICa–L." (PMID 41552678, 2025). "The authors also showed that there were two different mechanisms for Na+ entry during ischemia and reperfusion: a major pathway for Na+ entry during ischemia is the persistent Na+ channels (INa,P) and the major pathway for Na+ entry on reperfusion is NHE1." (PMID 30405433, 2018).
Obesity (2 papers, 2022 to 2024). Accumulation of substantial excess body fat. "In the context of available literature, our results suggest that INa regulation may be protective in obesity-related AF, but this only partially explains the benefit derived from SGK1 genetic inhibition." (PMID 35998035, 2022).
schizophrenia (2 papers, 2012). A major psychotic disorder characterized by abnormalities in the perception or expression of reality. "ACTB, CKB, NEFL, INA and GFAP had link to both schizophrenia and depression, while CTSD, HSPA8, NEFM and TUBA1A had link to schizophrenia." (PMID 23272063, 2012). "INA and DPYSL2 have been found differentially expressed in schizophrenia brains." (PMID 22350622, 2012).
Ventricular arrhythmia (2 papers, 2020 to 2025). "The data provided in this study and the evidence of its complex role in regulating multiple ion currents make LITAF an interesting target for innovative strategies in the prevention and treatment of ventricular arrhythmias, not least those associated with reduced Nav1.5 function and INa." (PMID 33093176, 2020).
adenoma (1 paper, 2011). A neoplasm arising from the epithelium. "Within 60 adenoma samples (median age 67 years) successfully amplified by qMSP, promoter hypermethylation was detected in 90%, 68%, 42%, 85% and 55% for CNRIP1, FBN1, INA, MAL, and SNCA, respectively, and 90% of the adenomas harbored co-methylation." (PMID 21777459, 2011). "Promoter hypermethylation of the genes CNRIP1, FBN1, INA, MAL, SNCA, and SPG20 was frequent in both colorectal cancers (65-94%) and adenomas (35-91%), whereas normal mucosa samples were rarely (0-5%) methylated." (PMID 21777459, 2011).
Alzheimer disease (1 paper, 2023). A progressive, neurodegenerative disease characterized by loss of function and death of nerve cells in several areas of the brain leading to loss of cognitive function such as memory and language. "Moreover, top hub genes in this module were associated with the development of Alzheimer’s disease, including VSNL1, INA, CHN1, NMNAT2, and MAP7D2." (PMID 37284017, 2023).
atrial fibrillation (1 paper, 2013). A disorder characterized by an electrocardiographic finding of a supraventricular arrhythmia characterized by the replacement of consistent P waves by rapid oscillations or fibrillatory waves that vary in size, shape and timing and are accompanied by an irregular ventricular response. "Knockout mutations in the SCN5A gene decrease INa and are associated with cardiac conduction diseases including Lenègre disease, BrS, sick sinus syndrome and atrial fibrillation (AF)." (PMID 23825462, 2013).
atrial tachycardia (1 paper, 2020). A disorder characterized by an electrocardiographic finding of an organized, regular atrial rhythm with atrial rate between 101 and 240 beats per minute. "Indeed, we detected more frequent atrial tachycardia induced by the atrial burst pacing, suggesting that the IK1 and INa remodeling might contribute to proarrhythmia propensity after the Fontan operation." (PMID 31912231, 2020).
B cell lymphoma (1 paper, 2023). "We saw the same gain of activity in a stomach cancer cell line and a B cell lymphoma cell line, both expressing similar levels of type I receptors as INA-6 and KARPAS-417, giving our results a relevance beyond multiple myeloma." (PMID 36717825, 2023).
cardiac arrest (1 paper, 2022). Cessation of breathing and/or cardiac function. "In the settings of severe infection, high levels of IL-6 combined with AZM and HCQ, can cause fatal arrhythmias and cardiac arrest via excessive conduction abnormalities, prolongation of the QTc and APD as a result of the multi-channels’ inhibition of INa, ICaL and IKr." (PMID 35058480, 2022).
cardiacischemia (1 paper, 2025). "INa inhibition is enhanced in pathological conditionssuch as myocardial ischemia." (PMID 40630435, 2025). "Therefore, cardiacischemia also affects INa expression by influencing the transport of Na+channels to the plasma membrane." (PMID 40630435, 2025).
Channelopathies (1 paper, 2021). "Channelopathies, such as mutations in the HCN4, SCN5A and KCNQ1 genes, which encode ion currents If, INa and IKs, can lead to reduced pacemaker rate." (PMID 34814734, 2021).
chronic heart failure (1 paper, 2019). "Briefly, in chronic heart failure the potassium channels (Ito, IKs, IKr and IK1) are downregulated, sodium channel (INa) shows a delayed inactivation, finally, calcium handling is deeply altered." (PMID 31447689, 2019).
colitis (1 paper, 2025). Inflammation of the colon. "We establish that Pdur and PR prolongation are the consequence of a reduced availability of Cx43 and the voltage dependent Na-channels (INa, SCN5A), and that a prolongation of the APD is the result of a colitis-induced attenuation of Ito." (PMID 40723857, 2025).
colon cancer (1 paper, 2011). "Before drug treatment all colon cancer cell lines tested harbored promoter methylation of CNRIP1, INA, FBN1, and SNCA accompanied by little or no expression of the same genes." (PMID 21777459, 2011).
colorectal adenoma (1 paper, 2011). An adenoma that arises from the colon or rectum. "We have identified four genes, CNRIP1, FBN1, INA, and SNCA that were frequently hypermethylated in colorectal adenomas and cancers." (PMID 21777459, 2011).
colorectal cancer (1 paper, 2011). A primary or metastatic malignant neoplasm that affects the colon or rectum. "CNRIP1, FBN1, INA, MAL, and SNCA promoter methylation was analyzed quantitatively (qMSP) in the colorectal cancer (n = 74; median age 71 years) and normal mucosa (n = 51; median age 55 years) test sets." (PMID 21777459, 2011). "Methylation in colorectal cancers ranged from 55% (C3orf14) to 96% (BEX1; median 84%), while methylation in normal tissue was between 0% (CNRIP1, FBN1, INA) and 45% (BEX1; median 5%), P < 0.0001 to P < 0.02." (PMID 21777459, 2011). "Co-methylation, here defined as simultaneous hypermethylation of two or more of the six gene promoters (CNRIP1, FBN1, INA, MAL, SNCA, and SPG20), was found in 99% of the colorectal cancer test set samples and 2% of the normal mucosa samples." (PMID 21777459, 2011).
Hypokalemia (1 paper, 2021). An abnormally decreased potassium concentration in the blood. "The longer term effects of hypokalemia were dominated by the interplay of IK1, INaK, INa, Vr, and [Na+]i." (PMID 34122128, 2021).
metastatic disease (1 paper, 2021). "In the present study, we analyzed DNA methylation of INA, NHLH2, and THBS4 in normal, tumor, and metastatic renal tissue samples and found tissue-specific hypermethylation associated with the metastatic disease state, adverse clinical parameters, and shorter PFS." (PMID 35008203, 2021). "Methylation of the INA, NHLH2, and THBS4 loci was also measured in a subset of 136–142 primary tumor tissues free of lymph node or distant metastasis and a total of 202 cancer metastatic tissues isolated from 100 renal cell cancer patients suffering from metachronous metastatic disease." (PMID 35008203, 2021).
periodontitis (1 paper, 2023). An acute or chronic inflammatory process that affects the tissues that surround and support the teeth. "No study has shown a relationship between the INA gene and periodontitis." (PMID 36982508, 2023).
psoriasis (1 paper, 2024). An autoimmune condition characterized by red, well-delineated plaques with silvery scales that are usually on the extensor surfaces and scalp. "By intersecting the differential genes identified in all four datasets, we identified 15 common genes that exhibited high expression in both BC and psoriasis, with the exception of INA, WIF1, and TIMP4." (PMID 38605947, 2024).
renal carcinoma (1 paper, 2021). A carcinoma arising from the epithelium of the renal parenchyma or the renal pelvis. "Thus, metastasis in RCC is significantly associated with methylation alterations in INA, NHLH2, and THBS4 loci, providing independent information for the potential early detection of aggressive renal cancers as a rationale for stratifying patients to adjuvant therapies." (PMID 35008203, 2021).
cancer (7 papers, 2011 to 2023). A tumor composed of atypical neoplastic, often pleomorphic cells that invade other tissues. "Other candidates, such as CD79B, MAP4K1, GRAP, TNFRSF13C, and INA, had comparable scores and are candidates for further study, as they have also been implicated in carcinogenesis of other cancer types." (PMID 28146432, 2017). "This includes pairs of hsa-miR-23b-3p and NACC1, a cancer-related transcription regulator, hsa-miR-23b-3p and PIK3R3, as well as hsa-miR-134-5p and INA gene that encodes neuronal intermediate filament involved in pituitary tumorigenesis." (PMID 32413978, 2020). "The level of mRNA expression of CNRIP1, FBN1, INA, and SNCA was strongly associated with promoter methylation status in cancer cell lines (P = 0.037, P = 0.017, P = 0.006, and P = 0.001, respectively)." (PMID 21777459, 2011). "This is very important because it suggests that the activity of NaVα, i.e., INa, might be more important than the molecular identity of the channel, and that broad spectrum inhibitors of NaV rather than some being very specific to isoforms, could be used to reduce cancer cell invasiveness." (PMID 26283962, 2015). "In spite of several genome-wide epigenetic studies, only a few reports include DNA methylation data and potential subsequent epigenetic silencing of CNRIP1, FBN1, INA, and SNCA in cancer." (PMID 21777459, 2011). "In human non-small-cell lung cancer cell lines it was found that the strongly metastatic H23, H460 and Calu-1 cancer cells possessed INa while the weakly invasive A549 and the non-cancer lung epithelial cells NL-20 and BEAS-2B did not." (PMID 26283962, 2015).
tumor (6 papers, 2008 to 2025). "Survival analysis using available follow-up data for a subset of tumors demonstrated a possible significant association of higher tumor methylation and shortened time to disease progression in univariate log rank analyses for INA, NHLH2, and THBS4 methylation." (PMID 35008203, 2021). "Western blotting highlighted positive staining for DCX and INA in tumor samples, and a lower expression of the mature neural marker NeuN, strongly suggesting the presence of immature neurons." (PMID 39717507, 2025). "For example, INA is a novel tumour suppressor that increases microtubule polymerization during CRC progression." (PMID 36117173, 2022). "Methylated TCGA KIRC based candidate CpG loci in INA, NHLH2, and THBS4 that are possibly associated with RCC metastasis were evaluated by pyrosequencing in 154 paired normal adjacent and primary tumor tissues, as well as in 202 metastatic tissues." (PMID 35008203, 2021). "To analyze whether the candidate genes have tumor-specific hypermethylation, we measured 120, 141, and 132 corresponding pairs of adN and tumor tissue specimens for methylation of INA, NHLH2, and THBS4." (PMID 35008203, 2021). "Here we found that the DNA methylation of CNRIP1, FBN1, INA, and SNCA was associated with reduced or lost gene expression in cell lines, indicating that they might harbor a tumor suppressor function." (PMID 21777459, 2011). "Furthermore, we have demonstrated that alpha-internexin (INA), a neuronal protein, was specifically expressed by 1p19q codeleted glioma tumor cells." (PMID 18492260, 2008).
infection (2 papers, 2013 to 2022). The state of being infected such as from the introduction of a foreign agent such as serum, vaccine, antigenic substance or organism. "In single NRVF, Ad-Kir2.1 or Ad-NaV1.5 infection enabled us to regulate the densities of IK1 and INa, respectively." (PMID 23393574, 2013).
cardiac disease (1 paper, 2017). "In the same settings of cardiac disease where KChIP2 is down, there are also observations of INa depletion." (PMID 28263709, 2017).
neurological diseases (1 paper, 2010). "More importantly, the OD of anti-INA Ab in CSF of NPSLE patients was significant higher than that of SLE-CI, SLE controls and neurological diseases controls." (PMID 20559547, 2010).
INA also shares sentences with these, for which no sentence is quoted: cardiac arrhythmias (5 papers); neurodegenerative disease (2); amyotrophic lateral sclerosis (1); astrocytoma (1); autism (1); autoimmune disease (1); brain glioma (1); cardiac hypertrophy (1); CNS tumor (1); Cognitive impairment (1); colon adenoma (1); dementia (1); dementia with Lewy bodies (1); depression (1); Down syndrome (1); ganglioglioma (1); glioblastoma (1); multiple myeloma (1); myocardial infarction (1); neuroendocrine neoplasm (1); ovarian carcinoma (1); Parkinson disease (1); renal cell carcinoma (1); Romano-Ward syndrome (1); short QT syndrome (1); sick sinus syndrome (1); stomach cancer (1).